SIRT3 (sirtuin 3)
Diseases named in the same sentence as SIRT3 in open-access papers (continued):
Sharing a sentence is not in itself a finding about the gene and the disease.
cancer (continued). "However, SIRT3 has been regarded as a double-edged sword for cancer therapy, which may increase the difficulty and risk of SIRT3 as a potential therapeutic target to some extent." (PMID 38773972, 2024). "In this Opinion paper we have elaborated on, and proposed that NO-dependent regulation of metabolism could go beyond this direct effect and influence key mitochondrial regulators, i.e., TRAP1 and SIRT3, which are involved in cancer-associated increase of antioxidant response and metabolic rewiring." (PMID 35959462, 2022). "Thus, as a potential marker, SIRT3 expression could be identified in patients susceptible to metastasis or drug-resistant disease when cancer is initially diagnosed." (PMID 35832551, 2022). "Several properties of SIRT3 may contribute to the outcome association in patients with cancer." (PMID 27483432, 2016). "To address the possibility of whether the association of SIRT3 expression and clinicopathological outcomes were cancer type specific, we further investigated the association of SIRT3 and other clinical parameters using total effect analyses and subgroup analyses grouped by cancer types." (PMID 27483432, 2016). "Indeed, the genetic loss of SIRT3 leads cancer cells to metabolic reprogramming towards glycolysis." (PMID 22666258, 2012). "IL-1β-IL-1R1 signaling is required for IEC SIRT3 deficiency-induced TH1 and CTL differentiation in cancer." (PMID 41487042, 2026). "In contrast, AA-induced ROS in cancer cells downregulates RelB, reducing SIRT3 and MnSOD levels, thereby amplifying oxidative and metabolic stress in cancer cells." (PMID 40940976, 2025). "In supporting this notion, we show here that Arg-II indeed induces DNA damage as reflected by enhanced p-γH2AX levels through decreased Sirt3/increased mtROS axis in both cancer cell types." (PMID 40177131, 2025). "SIRT3 is a potential therapeutic target due to its key role in various diseases, including ageing, heart disease, cancer, and metabolic disorders." (PMID 40338931, 2025). "Previously, SIRT3 was found to deacetylate lysine 321 (K321) of PDHA1 in cancer cells, K336 in skeletal muscle, and K83 in renal tubular epithelial cells and adipocytes." (PMID 41323268, 2025). "For instance, SIRT3 is overexpressed in head and neck squamous carcinomas, where its protective actions against ROS determine apoptosis prevention, which facilitates cancer." (PMID 39215785, 2025). "Intriguingly, HDAC inhibitors appear to inactivate HSCs, sensitize cancer cells to ferroptosis, and enhance the sensitivity of cancer cells to cisplatin therapy, while SIRT3 activators suppress HCC growth." (PMID 40867622, 2025). "Among these sirtuins, SIRT3 is the most potent mitochondrial deacetylase and plays a critical role in cancer development by modulating apoptosis, metabolism, and signaling pathways." (PMID 40885386, 2025). "This demonstrates a redox-dependent, SIRT3-mediated regulatory circuit in determining cancer cell fate." (PMID 41425553, 2025). "Immunosuppression, as a result of SIRT1 and SIRT3 activation, can reduce immune surveillance, thereby promoting cancer progression." (PMID 40673471, 2025). "There is evidence that SIRT3 regulates cellular iron metabolism and cancer growth by repressing iron regulatory protein 1 (aconitase)." (PMID 40298644, 2025). "Despite extensive characterization, the dualistic, context-dependent roles of SIRT3 in cancer biology remain incompletely resolved." (PMID 40860195, 2025). "Gene Set Enrichment Analysis from ChIP-seq data indicated SIRT3 regulated cell activation, cell adhesion, and nucleosome pathways in cancer through H3K9la levels." (PMID 40252727, 2025). "Our observations suggest roles for SIRT3 and SIRT7, both of which are NAD+‐dependent class III histone deacetylases implicated in various diseases, including cancer." (PMID 39873399, 2025).
cancer (continued). "This metabolic symbiosis, driven by hypoxia-inducible factor 1 (HIF1), is regulated by SIRT3, which influences the metabolic reprogramming of both CAFs and PCa cells, promoting cancer cell growth in glucose-deprived environments." (PMID 39796040, 2024). "Due of SIRT3's context-dependent role in different types of cancer, a variety of SIRT3 activators and inhibitors have been developed to regulate cancer growth." (PMID 38773972, 2024). "Through cancer research, it has been found that SIRT3 reduces ROS through the activation of transcription factors, particularly FOXO3a in adipocytes by expressing ROS-scavenging enzymes." (PMID 36952068, 2024). "The complex role of SIRT3 in cancer underscores the nuanced challenge of developing effective SIRT3 agonists and inhibitors as therapeutic agents." (PMID 38773972, 2024). "In fact, SIRT3 can activate the antioxidant defense system, and the lack of SIRT3 increases ROS signaling pathways, mediating carcinogenesis in several cancer types." (PMID 38931477, 2024). "A number of recent studies have shown that SIRT3 function varies among types of cancer in recent years." (PMID 39501597, 2024). "In summary, the precision in targeting, based on thorough molecular and cellular profiling of tumors, is essential to harness the potential of SIRT3 as a therapeutic target in cancer treatment." (PMID 38773972, 2024). "The precise impact of SIRT3 in cancer appears to be context-dependent, varying across cancer types and stages." (PMID 38562143, 2024). "Given the major role of SIRT3 in the regulation of cancer metabolism and mitochondrial homeostasis, its levels under iSGLT2 treatment in CRC cells were evaluated." (PMID 38811901, 2024). "According to reports SIRT3 also affects the role of the TCA cycle thereby promoting cancer development." (PMID 39479446, 2024). "As an oncogene or a tumor suppressor gene, SIRT3 plays an important role in the commencement and progression of certain cancers." (PMID 39501597, 2024). "In the context of KIRC, SIRT3 appears to maintain this role, though the specific effects are likely influenced by the cancer’s unique genetic and epigenetic makeup." (PMID 38794205, 2024). "SIRT3 loss enhances the expression of HIF-1α, a driver of hypoxia-mediated metabolic reprogramming in cancer, leading to an increased reliance on glycolysis and reduced oxidative phosphorylation." (PMID 39682281, 2024). "In triple-negative MDA-MB-231breast cancer cells, 19 and 20 increasedGDH activity, a known SIRT3 substrate activated by deacetylation,similarly or better than the effect showed by overexpressing SIRT3cells." (PMID 38261767, 2024). "In order to accelerate the targeting of SIRT3 for cancer therapy, it is necessary to apply these emerging drug design methods to the development of SIRT3 small molecule activators and inhibitors." (PMID 38773972, 2024). "Therapeutic strategies need to carefully consider the cancer type, stage, and the specific metabolic pathways involved to effectively utilize SIRT3 modulators." (PMID 38773972, 2024). "As such, in addition to direct effects of carnosine via free radical species scavenging, SIRT3 upregulation following carnosine exposure suggests additional potential SIRT3‐mediated anti‐cancer actions." (PMID 38018900, 2024). "Early studies also found that it can promote the expression of SIRT3 and inhibit a variety of cancer cells." (PMID 39598839, 2024). "Overall, despite several efforts to producing SIRT3 inhibitors, there is a shortage of small molecular compounds suitable for cancer treatment by targeting the inhibitor, which indicating that there are numerous problems in developing the SIRT3 inhibitor." (PMID 38773972, 2024). "In the present manuscript, we investigated the contribution of mitochondrial sirtuin 3 (SIRT3) to the adaptation and survival of cancer cells to a low pHe." (PMID 38931477, 2024).
cancer (continued). "A comprehensive understanding of the multifaceted role of SIRT3 is essential to effectively exploit its therapeutic potential in cancer." (PMID 38773972, 2024). "Numerous reports have indicated the involvement of SIRT3 in multiple diseases, including certain cancers, diabetes, and cardiovascular disease." (PMID 39501597, 2024). "Beyond energy metabolism, SIRT3 also exerts a significant influence on amino acid metabolism, thereby ensuring an adequate supply of amino acids for cancer cells and promoting tumorigenesis." (PMID 38773972, 2024). "As a result, many scientists are interested in finding ways to use small-molecule anti-cancer therapies that specifically target SIRT3." (PMID 38816444, 2024). "The suppression of SIRT3 is central to the metabolic reprogramming that fuels the rapid proliferation of cancer cells via enhanced glucose uptake and lactate production." (PMID 39682281, 2024). "The oncogenic role of SIRT3 is mainly related to the metabolic dependence mode and ROS preference degree of different cancers." (PMID 39479446, 2024). "SIRT3 influences cell proliferationand survival via various mechanisms depending on the cancer type.Nowadays, it is well established that ROS levels are generally lowerin normal cells compared to cancerous ones." (PMID 38261767, 2024). "In fact, the role of SIRT3 in cancer is somewhat controversial since this protein can work as both an oncogene and an oncosuppressor, depending on the cancer type and history." (PMID 38931477, 2024). "Overexpression of SIRT3 has been observed in different types of carcinomas, where it correlates with malignancy and a worse prognosis." (PMID 38931477, 2024). "In fact, SIRT3 is already being studied as a therapeutic target for several diseases, including cancer, and a series of small-molecule and other regulatory compounds targeting SIRT3 have been discovered or designed synthetically." (PMID 37345199, 2023). "Further studies should examine the effects of small molecules that target PROX1 on cancer cell metabolism and SIRT3 expression." (PMID 36594098, 2023). "Recent studies have demonstrated that the down-regulation of SIRT3 leads to the development of several diseases, such as neurodegenerative diseases, cancers, and heart disease." (PMID 37481555, 2023). "The expression of SIRT3 has been proposed as a putative early marker of cancer onset and as an independent criterion to stratify patients prone to develop chemoresistance or metastasis." (PMID 37735413, 2023). "For example, Albendazole, an anti-helminthic drug, exhibits an off-target effect by promoting SIRT3 degradation and thus cancer cell death." (PMID 37735413, 2023). "On these bases, SIRT3 activationwould be a fascinating approachfor the treatment of several diseases, including cancer." (PMID 37439550, 2023). "This combination induces oxidative stress-mediated apoptosis in cancer cells through the inhibition of the SIRT3/SOD2-Akt (SIRT3: sirtuin-3, SOD2: superoxide dismutase 2, Akt: serine/threonine kinase 1) pathway." (PMID 37630248, 2023). "SIRT3 has a crucial role in carcinogenesis, resistance to chemotherapy, cancer metastasis, and the regulation of metabolic reprogramming of cancer cells." (PMID 37735413, 2023). "Our findings are also relevant to human disease since we found a marked MST1 activation and SIRT3 reduction in myocardial specimens of patients with cancer treated with DOX-based therapy a few years earlier." (PMID 37566283, 2023). "With respect to genes CDK12 (CRKRS), CWC25 (CCDC49), GRB7, MIEN1 (C17orf37), PNMT and SIRT3, they have been shown to be linked to HER2 receptor and cancer." (PMID 37096121, 2023). "Our study presents a working model for LINC00922-mediated SIRT3 recruitment and H3K27cr modification in human cancer metastasis." (PMID 37789393, 2023). "Recent investigations have focused on SIRT3 due to its function in stress resistance, aging, neurodegenerative disease, and cancer." (PMID 37482618, 2023).
cancer (continued). "BALB/c nude mice were subcutaneously injected with cancer cells transfected/untransfected with SIRT3 overexpressing lentiviral vectors." (PMID 37747648, 2023). "SIRT3 is upregulated in some types of cancers, where it has been referred to as an oncogene preventing apoptosis and promoting cell proliferation." (PMID 35393510, 2022). "Many previous studies have established that SIRT3 regulates mitochondrial function and metabolism by increasing mitochondrial respiration, inhibiting glycolysis, and modulating cancer-cell proliferation." (PMID 35671305, 2022). "As shown here, SIRT3 can also restore mitochondrial functions, and improve the sensitivity of anti-cancer drugs in ccRCC cells." (PMID 35671305, 2022). "Although the most basic biological function of SIRT3 is the deacetylation of its substrate, cancer cell pathophysiology, metabolism reprogramming, metastasis, and chemoresistance are dependent on the regulation of SIRT3 deacetylation." (PMID 35832551, 2022). "Perhaps, combining SIRT3 activators/inhibitors with other drugs targeting a specific cancer type to design personalized therapy programs would be a potential treatment strategy." (PMID 35832551, 2022). "Regulation of metabolism reprogramming and EMT by SIRT3 can make a significant influence on cancer metastasis." (PMID 35832551, 2022). "SIRT3, regarded as a novel and potential therapeutic target, is shown to be involved in most of these cancer pathways." (PMID 35571098, 2022). "Using the knowledge obtained in the course of conducted experiments, we postulate consideration of Sirt3 as a target in the rising vulnerability of cancer cells during therapy and therefore increasing the effectiveness of cancer treatment." (PMID 35440893, 2022). "Existing studies support the dual role of SIRT3 in cancer development, suggesting that SIRT3 activators/inhibitors can be served as cancer treatments, which is a very attractive strategy for cancer therapy." (PMID 35832551, 2022). "In conclusion, SIRT3 is a promising biomarker and plays an essential role in different cancer types." (PMID 35832551, 2022). "The role of SIRT3 in cancer is mainly to remove excess ROS through deacetylating and activating its substrates." (PMID 35832551, 2022). "Among the sirtuins, Sirt3, a genomically expressed, mitochondrial-located tumor suppressor protein has an aberrantly low level of expression in various cancers including OCs where Sirt3 has anti-proliferative and anti-migratory effects." (PMID 36132133, 2022). "In the future, further exploration of the dual role of SIRT3 in cancer progression should be done as follows." (PMID 35832551, 2022). "A previous study discovered that 4-HNE’s angiogenesis function via the SIRT3-HIF-1-VEGF axis was associated with hypoxia in TME and resulted in cancer development and immune dysfunction via metabolic reprogramming and metabolic competition." (PMID 36144737, 2022). "Increased glycolysis and metabolic transformations are hallmarks of cancer cells, and the simple overexpression of SIRT3 improved cell sensitivity to our test drugs." (PMID 35671305, 2022). "The role of SIRT-3 in cancer is controversial and there are several reports describing its function as an oncogene as well as an oncosuppressor." (PMID 36080416, 2022). "The function of SIRT3 in aging, neurological disease, cancer, and stress resistance has drawn much attention." (PMID 35571098, 2022). "In this article, we review the multiple roles of SIRT3 in various cancers, and systematically summarize the recent advances in the discovery of its activators and inhibitors." (PMID 35571098, 2022). "Accumulating evidence has documented that SIRT3 ameliorates many types of human diseases, including cancer, heart disease, and metabolic disorder, indicating SIRT3 is a potential therapeutic target." (PMID 36010672, 2022). "In this section, we mainly discuss the therapeutic value of SIRT3 activators/inhibitors in cancer treatment." (PMID 35832551, 2022).
cancer (continued). "Sirt3 suppresses cancer progression and metastasis by controlling acetylation of several mitochondrial proteins including superoxide dismutase II (SOD II) via which it decreases ROS." (PMID 36344992, 2022). "HIF-1α is a transcription factor that controls glycolytic gene expression, and SIRT3 mediates metabolism reprogramming by destabilizing HIF-1α to affect the progression of cancer." (PMID 35832551, 2022). "As a natural anti-cancer agent, Resveratrol activates SIRT3 to regulate cancer at different stages, but the mechanism of action of Resveratrol is still unclear." (PMID 35832551, 2022). "Among the targets of Sirt3 is the transcription factor Forkhead box O3 (FOXO3a), one of the key regulators of cancer cell homeostasis." (PMID 35938164, 2022). "The high expression of SIRT3 correlates with a poor clinical prognosis in several cancers, including colorectal and gastric cancers." (PMID 36497084, 2022). "Of course, SIRT3 can significantly inhibit cancer metastasis via inhibiting ROS levels, EMT, and the Src/FAK signaling pathway." (PMID 35832551, 2022). "Selective inhibition of SIRT3 is promising in the development of anticancer drug by targeting a specific type of cancer with abnormal SIRT3 functions such AML and OSCC." (PMID 35433629, 2022). "Using the knowledge obtained in the course of conducted experiments, we postulate Sirt3 as a target in making cancer cells more vulnerable and increasing the effectiveness of cancer therapy, leading to a higher level of apoptosis." (PMID 35440893, 2022). "In ccRCC tissues, SIRT3 is downregulated and regulates the Warburg effect by shifting cancer-cell metabolism by destabilizing HIF1α." (PMID 35671305, 2022). "Studies using different cancer models to determine the precise role of SIRT3 in tumorigenesis have drawn different conclusions." (PMID 35571098, 2022). "Available data have confirmed the dual role of SIRT3 in cancer, and the effects of SIRT3 are different at different stages of cancer development, although the study of such phenomena remained unsystematic." (PMID 35832551, 2022). "In discovery of novel SIRT3 inhibitors for the treatment of cancer, a series of 2-(4-acrylamidophenyl)-quinoline-4-carboxylic acid derivatives were designed and synthesized." (PMID 35433629, 2022). "In discovery of potent SIRT3 inhibitors for the treatment of cancer, a series of compounds were designed and synthesized for the activity screening." (PMID 35433629, 2022). "The activation of the SIRT3 relative anti-oxidative pathway was proved to be the reason for the enhanced anti-cancer effects of cis-platinum and RES combination." (PMID 35865961, 2022). "SIRT3 dysfunction is related to several neurological conditions such as cancer, aging, metabolic disorder and neurodegenerative diseases." (PMID 36515436, 2022). "We will comprehensively review the mitochondrial substrates and functions of SIRT3, highlighting its dual role in various cancers, and summarize the activators and inhibitors of SIRT3 in this article." (PMID 35571098, 2022). "As an important intracellular regulatory factor of energy metabolism, SIRT3 has the ability of metabolism reprogramming and contributes greatly to cancer fate." (PMID 35832551, 2022). "On the other hand, a tumor suppressor role has been suggested for SIRT3 in several solid tumors based on findings showing that it prevented the reprogramming of cancer cell metabolism via the destabilization of hypoxia-inducible factor-1α." (PMID 36497084, 2022). "SIRT3 can coordinate complete shifts in mitochondrial metabolism and has a potential impact on diseases, especially CVDs and cancer." (PMID 35571098, 2022). "Based on the dual role of SIRT3 in cancer, its involvement in cancer drug resistance is also bidirectional." (PMID 35832551, 2022). "Zinc finger matrin-type 1 (ZMAT1), a member of the Cys2His2 (C2H2)-type zinc finger family, has been shown to contribute to the anti-cancer effects of SIRT3 in pancreatic ductal adenocarcinoma." (PMID 36497084, 2022).